MYH9 (myosin heavy chain 9)
Diseases named in the same sentence as MYH9 in open-access papers (continued):
Sharing a sentence is not in itself a finding about the gene and the disease.
infection (continued). "Consistently, the infection levels of HPV16 in HeLa-MYH9 cells could be reduced by using myosin-9 siRNA." (PMID 38242322, 2024). "A previous study showed that the C-terminal end (aa 1651–1960) of MYH9 (PRA) from PAM cells could block the infection by different PRRSV strains via interaction with GP5." (PMID 35694306, 2022). "Similarly, MYH9 promotes viral entry and infection by interacting with gB of HSV-1, Gn of SFTSV, and gH/gL of EBV in permissive cells (26, –28)." (PMID 34873039, 2021). "Moreover, MYH9 has been reported to act as a necessary cellular factor for infection with viruses such as herpes simplex virus-1 (HSV-1), thrombocytopenia syndrome virus (SFTSV), Epstein-Barr virus (EBV), and PRRSV." (PMID 31447818, 2019). "Thus, identifying the kinase(s) that activate MYH9 upon virus entry may provide new druggable targets to limit the early steps of infection of a variety of RNA viruses of public health importance." (PMID 41217108, 2025). "PP1 treatment did not further decrease viral internalization in siMYH9-transfected cells with respect to control cells, and the addition of the inhibitor reduced virus-triggered tyrosine phosphorylation of MYH9 during entry, suggesting that MYH9 may be activated by Src kinases upon infection." (PMID 41217108, 2025). "Thus, to test whether MYH9-PRA may promote infection of other CoVs in human lung cells, we infected NC and PRA-A549 cells with two αCoVs (HCoV-229E and HCoV-NL63) and three βCoVs (SARS-CoV-1, MERS-CoV, and HCoV-HKU1)." (PMID 34873039, 2021). "Therefore, S100A4 may effectively inhibit MYH9 aggregation, as supported by its efficacy in inhibiting infection of permissive cells by all PRRSV isolates tested." (PMID 31649651, 2019). "Moreover, the treatment of PAMs with the recombinantly expressed CD163 SRCR1-4 could significantly inhibit both PRRSV-1 and PRRSV-2 infections via competitive binding for MYH9 with the endogenous CD163." (PMID 31447818, 2019). "Upon infection with Herpes Simplex Virus-1 (HSV-1), MYH9, which is normally found in the cytoplasm, translocates to the cell surface." (PMID 40006922, 2025). "We found that the depletion of endogenous MYH9 not only significantly reduced the infection of SARS-CoV-2 pseudovirus but also reduced infection by the SARS-CoV-1 and MERS-CoV pseudovirus." (PMID 34873039, 2021). "We examined whether MYH9 may serve as an entry factor for TCRV and LCMV by analyzing its sub-cellular localization upon infection." (PMID 41217108, 2025). "The treatment of A549 cells with blebbistatin before and during infection resulted in a significant reduction in TCRV and LCMV RNA levels at 24 hpi, suggesting that the ATPase activity is necessary for the proviral function of MYH9." (PMID 41217108, 2025). "Moreover, the myosin heavy chain 9 (MYH9), which was targeted by CIGB-325, is another bona fide CK2 substrate whose phosphorylation at the S1943 is upregulated during infection of Vero-E6 cells by SARS-CoV-2." (PMID 35336959, 2022). "For example, if there is only a 2-fold excess of receptors for gB (MYH9) and gD (PVRL1 plus TNFRSF14), the differential efficiency of primary infection could rise 8×, and to 64× for a further round of infection." (PMID 27981441, 2017). "MYH9 was transcriptionally upregulated as early as 6 hpi; it reached peak expression at 12 hpi (3.29-fold), and then its expression decreased gradually as the HP-PRRSV infection progressed." (PMID 27686528, 2016). "In this study, we demonstrate that blocking of MYH9 with Mab2-5G2 significantly diminished PRRSV internalization by porcine alveolar macrophage (PAM) via interruption of direct interaction between GP5 and MYH9, and thus remarkably inhibited subsequent infection of PAMs by PRRSV-2 isolates." (PMID 31905776, 2019).
infection (continued). "Moreover, overexpression of S100A4, a MYH9-specific disassembly inducer, in MARC-145 cells significantly resulted in diminished MYH9 aggregation and marked inhibition of subsequent virion internalization and infection by both PRRSV-1 and PRRSV-2 isolates." (PMID 31649651, 2019). "In this study, we utilized APEX2 proximity-labeling techniques and identified nonmuscle myosin heavy chain IIA (MYH9) as an ACE2 coreceptor to promote SARS-CoV-2 infection of human lung cells, as well as infection of pan-coronavirus." (PMID 34873039, 2021). "At 72 hrs post infection, infectious PRRSV particles were also detected from the supernatant samples from MARC-145, PK-15CD163, or COS-7CD163+MYH9 cells, but not in PK-15puro, COS-7puro, or COS-7CD163 cell supernatant samples." (PMID 27112594, 2016). "Interestingly, introduction of S100A4 protein expression within MARC-145 cells significantly diminished MYH9 aggregation and ultimately inhibited PRRSV internalization and sequential infection regardless of PRRSV genotype." (PMID 31649651, 2019). "PRRSV and MYH9 were located together in MARC-145 cells and PAMs between 15 min to 2 hrs after the cells were shifted to 37 °C, but not after 4 hrs post infection." (PMID 27112594, 2016).
autosomal dominant disease (7 papers, 2014 to 2025). Autosomal dominant form of disease. "Mutations in the MYH9 gene that encodes NM2A cause MYH9-related disease, an autosomal dominant disease that affects approximately one in 312,000 people." (PMID 38042490, 2023). "MYH9-related disease or disorder (MYH9-RD) is an autosomal dominant disease caused by mutations in the MYH9 gene." (PMID 34394193, 2021). "It was first discovered in a number of autosomal dominant diseases, in which genetic mutations in MYH9 gene resulted in thrombo-cytopenia." (PMID 34425650, 2021). "May-Hegglin anomaly (MHA) is a rare autosomal dominant disease associated with a mutation in the MYH-9 gene." (PMID 39588168, 2024). "The rare autosomal dominant disease associated with the MYH-9 gene mutation is May-Hegglin anomaly (MHA)." (PMID 39588168, 2024). "There is a lack of awareness of the diagnosis and treatment of MYH9-related disorder (MYH9-RD), which is an autosomal dominant disease with heterogeneous clinical manifestations." (PMID 40416435, 2025).
genetic disease (6 papers, 2016 to 2025). "MYH-9 related disease (MYH9-RD) is a rare genetic disorder caused by mutations in the MYH-9 gene, which encodes the myosin heavy chain 9 component of non-muscle myosin IIA (NMMHC-IIA)." (PMID 32227072, 2020).
blood disorders (5 papers, 2021 to 2026). "Mutations in MYH9 cause a spectrum of blood disorders collectively termed MYH9-related diseases (MYH9-RD)." (PMID 40475454, 2025). "Mutations in the MYH9 gene, which encodes the heavy chain of the actin-based molecular motor non-muscle myosin II-A (NM2-A), cause a spectrum of rare blood disorders collectively termed MYH9-related diseases (MYH9-RD)." (PMID 41760963, 2026). "Mutations in the MYH9 gene, which encodes the actin-based molecular motor non-muscle myosin II-A (NM2-A), cause a group of blood disorders termed MYH9-related diseases (MYH9-RD)." (PMID 40475454, 2025). "In addition to hematological changes, MYH9-RDs commonly present with various non-hematological disorders, and the severity and manifestation of these conditions can vary over time." (PMID 38134071, 2023). "Myosin heavy chain 9 (MYH9) has a documented role in various diseases, including hereditary diseases, hematologic diseases, and inflammatory conditions." (PMID 37892851, 2023).
adenocarcinoma (3 papers, 2015 to 2023). A common cancer characterized by the presence of malignant glandular cells. "In 230 patients with adenocarcinoma from the TCGA cohort, higher expressions of MYH9, GNB1, and ALOX12B were associated with poor overall survival outcomes, while higher expression of HSD17B4 was associated with better survival outcomes." (PMID 36612298, 2023). "In the present study, MYH9 was expressed in 102 of 266 (38.3%) NSCLCs, and its expression was significantly correlated with an adenocarcinoma histology, poorer differentiation, and intratumoral vascular and lymphatic invasion." (PMID 25826333, 2015). "MYH9 expression was significantly correlated with the adenocarcinoma histology (P = 0.014), poorer differentiation ((P = 0.033), intratumoral vascular invasion and lymphatic invasion ((P = 0.013 and P = 0.045 respectively), and a poorer prognosis ((P = 0.032)." (PMID 25826333, 2015). "We have reported that MYH9 is expressed in a subset of NSCLC, and its expression is related to the adenocarcinoma histology, poorer differentiation, intratumoral vascular invasion, intratumoral lymphatic invasion, and a poorer prognosis." (PMID 25826333, 2015).
brain diseases (1 paper, 2024). "The findings presented above demonstrate that the endothelial-specific knockout of Myh9 disrupts the integrity of the BBB, and this disruption exacerbates damage caused by brain diseases." (PMID 39404399, 2024).
gastrointestinal disease (1 paper, 2017). A disease that occurs in the gastrointestinal system, excluding the hepatobiliary system. "It was also reported MYH9 expression is associated with inflammation of gastrointestinal diseases." (PMID 27437869, 2017).
infectious disease (1 paper, 2025). A disorder directly resulting from the presence and activity of a microbial, viral, or parasitic agent in humans. "We also identified activation of the PSME4-related infectious diseases response pathway, marked by MYH9 phosphorylation at S1943." (PMID 40842862, 2025).
neurological disorders (1 paper, 2024). "Initial research on MYH9-RD primarily focused on hematological abnormalities, such as coagulation dysfunctions, with limited studies on neurological disorders." (PMID 39404399, 2024).
MYH9 also shares sentences with these, for which no sentence is quoted: HIV-associated nephropathy (7 papers); Hearing impairment (5); Wiskott-Aldrich syndrome (5); glomerulopathy (4); glomerulonephritis (3); hearing disorder (3); Usher syndrome (3); Alzheimer disease (2); chronic periodontitis (2); diffuse large B-cell lymphoma (2); escherichia coli infection (2); Fabry disease (2); fibrosis (2); intellectual disabilities (2); vasculopathy (2); Von Willebrand disease (2); active tuberculosis (1); acute lymphoblastic leukemia (1); adenosquamous cell carcinomas (1); age-related macular degeneration (1); Alpha-thalassemia (1); Alström syndrome (1); AMeD syndrome (1); anaphylaxis (1); anaplastic thyroid carcinomas (1); angioedema (1); aplastic anemia (1); astroblastoma (1); autoimmune disease (1); autoimmune thrombocytopenia (1).
A further 78 diseases each share a sentence with MYH9 in 1 paper.